INS (insulin)
Diseases named in the same sentence as INS in open-access papers (continued):
Sharing a sentence is not in itself a finding about the gene and the disease.
diabetes (continued). "Diabetes mellitus (DM) is a chronic, metabolic disease characterized by elevated blood glucose levels due to defects in insulin secretion, insulin action, or a combination of both." (PMID 36465216, 2022). "A recent study on phytochemicals has shown that curcumin is actively involved in decreasing insulin resistance, HbA1c and fasting insulin, leading to effective diabetes management." (PMID 35807304, 2022). "Nowadays, paying attention to insulinemic response along with glycemic response using an insulin index is much more effective in better metabolic control of diabetes." (PMID 36364951, 2022). "Protein tyrosine phosphatase 1B (PTP1B) has been recognized as a potential target for insulin sensitizing for the treatment of diabetes." (PMID 36431993, 2022). "Presently, available therapies for the management of diabetes include insulin and oral anti-diabetic agents such as biguanides, sulfonylurea, glinides and α-glucosidase inhibitors." (PMID 35831936, 2022). "Although initially purified from animal sources, recombinant sources of human insulin are now the main preparations used for the treatment of diabetes." (PMID 36555450, 2022). "In this approach, people with diabetes routinely inject themselves with long-lasting dosages, which can be supplemented with added fast-acting insulin dosages to regulate their blood glucose levels." (PMID 36381916, 2022). "Unexpectedly however, and not explained by expression of the KATP mutation, insulin content was markedly reduced (>50%) at day 15 of diabetes, correlating with decreased insulin immunostaining." (PMID 35180212, 2022). "According to the American Diabetes Association (ADA), “Diabetes is a very chronic situation which is characterized by high blood sugar, poor insulin secretion and the development of insulin resistance”." (PMID 35698061, 2022). "These proteins can function as antioxidants to repair molecules that are oxidized by reactive oxidative intermediates, which can preserve the expression of MAFA and insulin, and improve β-cell function in diabetes mouse models." (PMID 35562869, 2022). "Type 2 diabetes mellitus is a metabolic disorder resulting from impaired insulin secretion and resistance." (PMID 36440220, 2022). "At baseline, the mean (SD) duration of diabetes was 8.6 (5.6) years; duration of diabetes was longer in the insulin‐treated participants compared with insulin‐naïve participants (mean [SD]: 11.3 [6.6] and 7.7 [5.0] years, respectively)." (PMID 34856077, 2022). "It has been found that PIK3R1 can affect insulin signaling transduction and thus play a direct role in the development of diabetes through insulin resistance signaling." (PMID 35990823, 2022). "The purpose of the current study was to analyze the effect and the underlying genetic cause of the diabetes QTL Nidd13/NZO on chromosome 13, a key QTL associated with higher blood glucose levels and increased pancreatic insulin." (PMID 35328627, 2022). "Metformin has good effects on lowering glucose, improving insulin sensitivity and lipid profile, reducing cardiovascular events and mortality, and preventing progression to heart failure in patients with diabetes." (PMID 36465607, 2022). "This review aims to examine the reported glucose-lowering effect of the herb, with a keen focus on insulin secretion, specifically related to type 2 diabetes mellitus." (PMID 35053127, 2022). "Lipohypertrophy (LH) of subcutaneous tissue is an insulin-induced complication occurring in patients with diabetes." (PMID 35111222, 2022). "In the UKPDS, 3867 patients with newly diagnosed diabetes mellitus type 2 were randomly assigned to an intensive glucose-lowering strategy with sulfonylurea derivates or insulin versus a conventional glucose-lowering strategy with diet." (PMID 34097240, 2022). "Subgroup analyses were performed for age, sex, diabetes duration, insulin use, three or more antidiabetic drugs, hypertension, and dyslipidaemia." (PMID 36465437, 2022).
diabetes (continued). "Gut microbiota was associated with several diabetes-related metabolic markers including HOMA2-β, fasting plasma glucose, HbA1c and fasting insulin." (PMID 36466492, 2022). "These proteins are crucial factors in a proper insulin signaling pathway, and their downregulation results in insulin resistance and metabolic disorders like diabetes." (PMID 35340328, 2022). "It is a negative modulator of insulin signaling and has been recognized as a potential target for insulin sensitizing for the treatment of diabetes." (PMID 36431993, 2022). "While the injection attacked it (diabetes), the disease strikes me in retaliation for the injection's (insulin’s) attack; revenges me." (PMID 35854336, 2022). "Studies investigating long-duration (>20–50 years) diabetes suggest some individuals have residual beta-cells with the functional capacity to secrete insulin (C-peptide)." (PMID 36181724, 2022). "The mechanism through which PON-1 protected against diabetes was promoting β-cell viability, increasing β-cell’s insulin content, and promoting insulin release from β-cell." (PMID 35055468, 2022). "Consistent with previous studies, duration of diabetes, uncontrolled blood sugar level, insulin usage, obesity, and diabetes-related complications were negatively associated with HRQoL." (PMID 35180266, 2022). "In DIY diabetes movements, patients have hacked together an artificial pancreas from their glucose monitors and insulin pumps." (PMID 36632334, 2022). "Different reports have shown that in diabetes, the islets appear to be preferentially affected by the destruction of insulin-secreting β-cells." (PMID 35720184, 2022). "PPARG plays diverse roles in the pathogenesis of diabetes, regulating adipogenesis, lipid metabolism, insulin sensitivity, and inflammation." (PMID 35343389, 2022). "Hyperglycemia, systemic insulin resistance, and impaired cardiac insulin metabolic signaling are the major clinical abnormalities in all diabetes patients." (PMID 36552599, 2022). "Insulin combined with steroid therapy can partially rescue diabetes-induced imbalance in hormones and angiogenesis." (PMID 35029893, 2022). "Physicians prefer premixed insulin as a short-term simplified intensification therapy, and its use increases when patients have poor glycemic control, including diabetes complicated with CRD." (PMID 36093107, 2022). "Consuming food with resistant starch effectively lowers the postprandial blood glucose level, increases insulin sensitivity, and regulates insulin resistance for patients with diabetes mellitus." (PMID 35465219, 2022). "Type 2 diabetes mellitus (T2DM) is always characterized by abnormal blood glucose levels, a phenomenon caused by the general dysfunction between the action and secretion of insulin." (PMID 35269827, 2022). "Increasingly islet autoantibody markers are being recommended and performed clinically to inform diabetes classification and insulin treatment, particularly in older individuals where type 2 diabetes is most prevalent." (PMID 36181724, 2022). "In the present study, FBS and fasting insulin levels were used to evaluate the indicators related to diabetes, which showed a statistically significant difference between them and NAFLD." (PMID 35974947, 2022). "Impairment in insulin signaling, including insulin deficiency (type 1 diabetes mellitus, T1DM) and insulin resistance (type 2 diabetes mellitus, T2DM), affect not only peripheral tissues but also brain functions that are involved in AD pathologies." (PMID 35701718, 2022). "As a result, digital technology like CGMs, insulin pumps, and automated insulin delivery systems are increasingly prescribed and used by persons with diabetes to reduce the occurrence of adverse health events and the burden of management." (PMID 35941355, 2022).
diabetes (continued). "Unlike the anabolic treatments, the effect of insulin on bone was not a direct effect and was more based on the potentially paracrine effect of the insulin-induced rescue of circulating miRNAs in synergy with the metabolic regulation of diabetes." (PMID 35742976, 2022). "Canagliflozin is an insulin-independent glucose-lowering compound that is used for diabetes patients due to its convenient influence on the renal and cardiovascular." (PMID 36572938, 2022). "Diabetes mellitus (DM) is a metabolic condition associated with abnormally increased glucose levels in the blood, which is a consequence of the scarce production or action of insulin." (PMID 35807828, 2022). "Both pancreatic endocrine (i.e. production of hormones such as insulin) and exocrine (i.e. production of enzymes to aid digestion) functions are critical for nutritional metabolism and in chronic diseases including diabetes." (PMID 36300035, 2022). "Insulin levels decreased in those with a longer diabetes duration (p = 0.035), which translated into a similar reduction in the IGR (p = 0.019)." (PMID 36056607, 2022). "Participants' knowledge about important aspect of diabetes definition such as impaired insulin secretion and defective insulin action were insufficient." (PMID 35756103, 2022). "Among subjects with diabetes, body weight, BMI, waist circumference, eGFR, and the proportion of subjects taking insulin therapy were higher in subjects with PN compared with those without PN." (PMID 35651981, 2022). "When transplanted into diabetic mice, converted human α cells reversed diabetes and continued to produce insulin even after 6 months." (PMID 36551213, 2022). "Though initiation of insulin results in a significant change in glycemic levels, treating patients without significant hypoglycemic events remains difficult in diabetes patients initiated with different insulin-based regimens." (PMID 36149907, 2022). "Beta cells of the pancreas secrete insulin and its specific and selective destruction is the main characterized feature of type 1 diabetes mellitus (T1DM)." (PMID 35807304, 2022). "The anti-hyperglycemic effect of SGLT2i, which is different from many other antidiabetic agents, is a completely insulin-independent mechanism of action, which allows for the drugs to be used both in the early and late stages of diabetes." (PMID 36531469, 2022). "We identified the genus Lactobacillus and carbohydrate metabolism, as well as the insulin signaling pathway, as biomarkers and candidate therapeutic targets for diabetes." (PMID 36532503, 2022). "Diabetes mellitus is characterized by alterations in carbohydrate, protein, and lipid metabolisms due to insulin secretory defects, insulin action or both." (PMID 36460661, 2022). "The main symptom of type 2 diabetes mellitus (T2DM) is insulin (INS) resistance accompanied by a relative or absolute insufficiency of INS secretion, which leads to metabolic disorders of sugar, fat, and protein." (PMID 36619301, 2022). "Similar results were observed when comparing use of insulin alone or in combination with oral diabetes medications or use of oral diabetes agents alone or in combination with insulin." (PMID 35583495, 2022). "In mice with streptozotocin-induced diabetes, 2-O-M significantly prolonged the blood glucose-lowering effect of insulin, significantly reduced the secretion of exogenous insulin, and reduced the blood glucose concentration in vivo." (PMID 35502441, 2022). "Based on blood biochemical analyses, the two extracts play an important role in regulating the diabetes-induced lipid metabolism disorder, increasing the levels of insulin and C-peptide, and alleviating the symptoms of diabetes." (PMID 35224106, 2022). "Results of this study show that kidney disease increases with older age (p=0.010), longer duration of diabetes (p=0.005), therapy with a combination of OHAs and insulin (p=0.006), hypertension (p=0.003), and hypolipidemia treatment (p=0.001)." (PMID 35655685, 2022).
diabetes (continued). "Resveratrol significantly improves insulin sensitivity and glucose homeostasis, therefore it is a novel addition to diabetes and its sequelae treatments." (PMID 35806147, 2022). "Current diabetes therapy includes the use of insulin and hypoglycemic drugs, as well as dietary correction." (PMID 36246880, 2022). "Diabetes treatment requires intake of medication or injection with insulin, including lifestyle modifications regarding healthy food consumption and physical activity." (PMID 36564779, 2022). "Currently, the most widely used therapeutic for diabetes control is based on the endogenous hormone, insulin, and its analogues." (PMID 35335929, 2022). "The people with T2DM had poor total diabetes knowledge, general diabetes knowledge, and insulin use knowledge." (PMID 36527016, 2022). "The prevalence rates of the use of new technologies in this present study for mobile health applications, flash monitoring, blood glucose monitoring, and insulin pumps among the studied patients with diabetes were 13.5%, 12.2%, 11.3%, and 4%, respectively." (PMID 35719798, 2022). "The relationship between vitamin D and diabetes has been widely studied regarding the effect of vitamin D on β-cell function and insulin sensitivity." (PMID 36421415, 2022). "Firstly, the fasting blood glucose and insulin levels haven't included in this survey as they are the indicators of pre-diabetes." (PMID 36159247, 2022). "Insulin prescription can be a factor to differentiate diabetes severity but the small number of immigrants having insurance prescription precluded a further analysis." (PMID 35486634, 2022). "In the total population, the prevalence of high risk for diabetes was significantly increased by BMI, subjective health perception, average weekly sleep time, SBP, FPG, HbA1c, insulin, TG, and uric acid." (PMID 36010139, 2022). "NLRP3 inflammasome, IL-1β, and IL-18 can affect blood glucose control and insulin resistance, which are related to the pathogenesis of diabetes, and play an important role in diabetes-induced systemic chronic inflammation and insulin signal transduction." (PMID 36248820, 2022). "As expected, diabetes treatment focused on glucose-responsive release is a common approach, allowing for a self-regulated release of insulin to avoid burst release and its consequences, such as hypoglycaemia." (PMID 36671612, 2022). "In elderly patients with diabetes, studies have found that chronically reduced insulin secretion, low insulin concentrations, or high glucagon levels can lead to impaired insulin signaling in the brain." (PMID 35833084, 2022). "Diabetes mellitus is a chronic condition in which the level of glucose in the blood is raised because the body cannot produce any or enough insulin or cannot make efficient use of the insulin it produces." (PMID 36292966, 2022). "The prevention of hypoglycemia, a frequent and potentially life-threatening complication of insulin therapy, remains a priority in diabetes care." (PMID 36013211, 2022). "Majority 18 (75.0%) of the respondents reported that the biggest struggles they encounter with self-management of diabetes mellitus are daily checking of blood sugar and self-injection with insulin including restriction to their favorite meal." (PMID 35590021, 2022). "Although administration of anti-CD6 antibodies in combination with oral insulin was shown to be protective of diabetes in new onset diabetes in mice, the function of CD6 in monocytes has not been described." (PMID 35851422, 2022). "Even after the discovery and mass production of insulin, dietary carbohydrate remained restricted in the diet of people with diabetes." (PMID 35536220, 2022). "Distressed housing has been found to hinder self-care, as well as the acquisition of insulin and other diabetes supplies and equipment, as well as the consumption of food that is nutritionally balanced." (PMID 35619856, 2022).
diabetes (continued). "Despite the advent of type 2 diabetes (T2D) remission strategies and novel therapeutic agents, many individuals with T2D will require insulin treatment to achieve target glycemia, with the aim of preventing or delaying diabetes complications." (PMID 36197724, 2022). "Third, some women were treated with insulin, whereas others had diabetes under control with diet and exercise alone." (PMID 36431006, 2022). "β cell vulnerability to free fatty acids (i.e., lipotoxicity) reduces insulin provision and leads to diabetes." (PMID 35254894, 2022). "Diabetes mellitus (DM) is a group of metabolic disorders characterized by chronic hyperglycemia which results from defects in insulin secretion and/or insulin resistance over a prolonged period of time." (PMID 35694215, 2022). "Clinicians must ask people with diabetes if they have difficulty accessing or affording insulin and provide resources at appointments." (PMID 35436214, 2022). "In contrast, worries about complications of poorly controlled diabetes and beliefs that insulin was effective resulted in acceptance of insulin therapy." (PMID 35172774, 2022). "In fact, KD increased the insulin sensitivity in patients suffering with type 2 diabetes mellitus by about 75%." (PMID 36139562, 2022). "Impaired insulin signaling in the brain due to diabetes mellitus has a role in Alzheimer disease pathogenesis, suggesting that Alzheimer disease is a metabolic brain disease." (PMID 37551286, 2022). "SMS text message contact to help underserved patients with diabetes find their optimal basal insulin dose." (PMID 35060909, 2022). "A lower BMI coupled with the decrease of insulin secretion before the onset of diabetes is the pre-diabetic physiologic state of individuals with HNF1A-T2D." (PMID 35299962, 2022). "Diabetes mellitus is a metabolic disorder in which impairment of insulin secretion, defective insulin action, or both lead to hyperglycemia." (PMID 36148044, 2022). "In multivariable Tobit regression models older age, having poor glycemic control, longer duration of diabetes, insulin usage, obesity, and having diabetes-related complications were significant negative predictors of HRQoL." (PMID 35180266, 2022). "Most insulin injections for people with diabetes are administered at home, thus generating many used needles." (PMID 36568796, 2022). "Otherwise, currently, most people with diabetes are still using the traditional drug treatments with metformin, sulphonylureas and insulin, as in our cohort." (PMID 35568947, 2022). "He published a review in Physiological reviews in 2018, detailing the electrophysiology of beta cells and insulin secretion and offering new ideas for intervening in ion channels to treat diabetes." (PMID 36743933, 2022). "A well-known additional form of monogenic diabetes is neonatal diabetes, a rare disorder characterized by marked insulin-requiring hyperglycemia within the first 6 months of life." (PMID 35052457, 2022). "If the body maintains high glucose levels, then it will continuously stimulate insulin secretion, leading to islet cell failure with insufficient insulin secretion, and eventually to diabetes." (PMID 36034672, 2022). "The effect of STZ-induced diabetes on vitamin D 25-hydroxylase activity was partially prevented by insulin treatment." (PMID 35524739, 2022). "Intranasal insulin is a novel treatment for TII diabetes, which has demonstrated promising results in AD, as it improves brain insulin signaling and, consequently, ameliorates the cognitive performance and metabolic integrity of the brain in patients with AD." (PMID 35443732, 2022). "The choice of insulin as a means of taking one’s life often comes from its availability among the people suffering from diabetes." (PMID 35324747, 2022). "Most patients had long diabetes duration (> 5 years, 71.6%) and suboptimal glucose control (HbA1c > 7.5%, 76.2%); one half was under insulin treatment (50.2%) and 15.8% were treated with lifestyle interventions only." (PMID 36335346, 2022).